WTAPP1 (WTAP pseudogene 1 )
Gene: Long non-coding RNA gene on chromosome 11 (102,746,968 to 102,836,766, forward strand). Ensembl gene ENSG00000293047.
Diseases named in the same sentence as WTAPP1 in open-access papers:
WTAPP1 is named in the same sentence as 5 diseases in open-access papers, as found by Europe PMC text mining. Sharing a sentence is not in itself a finding about the gene and the disease. The quoted sentences say what the papers report.
non-small cell lung carcinoma (1 paper, 2020). A group of at least three distinct histological types of lung cancer, including non-small cell squamous cell carcinoma, adenocarcinoma, and large cell carcinoma. "Our study was therefore carried out to investigate the role of WTAPP1 in non-small cell lung cancer (NSCLC)." (PMID 32473628, 2020).
pancreatic ductal adenocarcinoma (1 paper, 2022). An infiltrating adenocarcinoma that arises from the epithelial cells of the pancreas. "WTAPP1 was significantly elevated in pancreatic ductal adenocarcinoma and is associated with a poor patient prognosis, and promotes the proliferation and invasive ability of the cells." (PMID 36139062, 2022). "Mechanistically, increased WTAPP1 mRNA levels in pancreatic ductal adenocarcinoma are caused by m6A modification, which stabilizes WTAPP1 mRNA by recruiting the RNA stabilizer HuR by CCHC-type zinc finger nucleic-acid-binding protein (CNBP)." (PMID 36139062, 2022).
Wilms tumor (1 paper, 2015). An embryonal neoplasm characterized by the presence of epithelial, mesenchymal, and blastema components. "WTAPP1, a pseudogene with unknown function, has been reported to be associated with Wilms’ tumor." (PMID 26247464, 2015).
tumor (3 papers, 2020 to 2023). "Here in PC, WTAPP1 was markedly overexpressed in tumor tissues, which was correlated with poor prognosis of PC patients." (PMID 35936737, 2022). "Compared to healthy tissues, expression levels of WTAPP1 were significantly higher in tumor tissues (p < 0.05)." (PMID 32473628, 2020). "It was observed that the expression of HAND2-AS1 in tumor tissues was significantly correlated with the expression of WTAPP1." (PMID 32473628, 2020). "According to Youden’s index, patients were divided into high (n = 36) and low (n = 32) WTAPP1 expression (tumor tissue) groups, compared to patients in the low WTAPP1 expression level group, patients in the high WTAPP1 expression group level showed significantly lower overall survival rate." (PMID 32473628, 2020).
cancer (1 paper, 2020). A tumor composed of atypical neoplastic, often pleomorphic cells that invade other tissues. "It has been reported that WTAPP1 can promote angiogenesis and migration of endothelial progenitor cells, while its functionality in cancer biology is unknown." (PMID 32473628, 2020). "WTAPP1 may promote cancer cell invasion and migration in NSCLC by downregulating lncRNA HAND2-AS1." (PMID 32473628, 2020). "In conclusion, WTAPP1 is upregulated in NSCLC and promotes NSCLC by downregulating HAND2-AS1 to promote cancer cell migration and invasion." (PMID 32473628, 2020). "We reported that WTAPP1 was upregulated in NSCLC, and WTAPP1 may serve as an oncogene in NSCLC by promoting cancer cell invasion and migration through the downregulation of HAND2-AS1." (PMID 32473628, 2020).